PABPN1 (poly(A) binding protein nuclear 1)
Diseases named in the same sentence as PABPN1 in open-access papers (continued):
Sharing a sentence is not in itself a finding about the gene and the disease.
colorectal cancer (6 papers, 2020 to 2025). A primary or metastatic malignant neoplasm that affects the colon or rectum. "We previously found that the LLPS droplets of PABPN1 were significantly reduced in colorectal cancer, which promoted the usage of proximal poly(A) sites of CTNNBIP1 and increased cell proliferation and migration." (PMID 40052530, 2025). "The splicing factor SNRPD2, which is upregulated in colorectal cancer, disrupts PABPN1 LLPS by interacting with PABPN1." (PMID 40052530, 2025). "Next, we investigated the role of QKI/PABPN1 axis in colorectal cancer cell proliferation and migration." (PMID 40052530, 2025). "Decreased expression levels and reduced nuclear localization of QKI in colorectal cancer cells attenuate PABPN1 LLPS, thereby promoting proximal APA sites, cell proliferation, and migration." (PMID 40052530, 2025). "Knockdown, overexpression and the KH domain mutant of QKI showed that QKI represses cell proliferation and migration in colorectal cancer cells, and these effects are also PABPN1-dependent to a certain extent." (PMID 40052530, 2025). "In this study, we found that the reduced QKI expression and nuclear localization in colorectal cancer cells disrupt PABPN1 LLPS, promoting the usage of proximal poly(A) sites, cell proliferation and migration." (PMID 40052530, 2025). "Furthermore, the reduction of QKI expression and nuclear localization in colorectal cancer cells leads to decreased PABPN1 LLPS and shortened 3′ UTRs of other genes, which further promotes cell proliferation and migration." (PMID 40052530, 2025). "Furthermore, the reduced expression level and nuclear localization of QKI in colorectal cancer cells negatively impacts PABPN1 LLPS, subsequently leading to increased usage of proximal APA sites and enhancing the proliferation and migration rates of cancer cells." (PMID 40052530, 2025). "Moreover, PrognoScan analysis revealed a correlation between higher PABPN1 expression and worse survival outcomes in many cancer types, including blood cancer (B-cell lymphoma), lung cancer, breast cancer, bladder cancer, esophagus cancer, brain cancer and colorectal cancer." (PMID 40607380, 2025). "Given the reduced LLPS droplets of PABPN1 in colorectal cancer cells, we further investigated whether enhanced nuclear localization of QKI promotes PABPN1 LLPS." (PMID 40052530, 2025). "Although no role for linear PABPN1 species in cancer has yet been reported, a circular RNA deriving from this locus has been reported to enhance colorectal cancer development by attenuating the activity of the splicing factor SRSF1 via the miR-638 axis." (PMID 36033512, 2022). "Furthermore, QKI exhibits decreased expression levels and diminished nuclear localization in colorectal cancer cells, resulting in reduced PABPN1 phase separation, which, in turn, promotes alternative polyadenylation (APA), cell proliferation, and migration in colorectal cancer." (PMID 40052530, 2025).
breast carcinoma (5 papers, 2020 to 2025). "The depletion of CPSF1 or PABPN1 weakened cell proliferation, enhanced apoptosis, resulted in cell cycle redistribution and a reversion of APA events of genes associated with tumorigenesis, proliferation, metastasis and chemosensitivity in breast cancer." (PMID 32929364, 2020).
prostate carcinoma (5 papers, 2022 to 2025). A carcinoma that arises from epithelial cells of the prostate gland. "In prostate cancer, a novel risk model comprising five genes, namely poly(rC) binding protein 1 (PCBP1), PABPN1, protein tyrosine phosphatase receptor type F (PTPRF), differentiation antagonizing non-protein-coding RNA (DANCR), and MYC, was established for predicting progression-free survival (PFS)." (PMID 40607380, 2025). "Additionally, our findings demonstrated noteworthy differences in PABPN1 expression across clinical subgroups of urogenital cancers, aligning with prior research highlighting varying PABPN1 expression in different stages of prostate cancer." (PMID 40607380, 2025). "With siRNA screens, several of these were indicated in survival (DDX6, EIF4A3, PABPN1), growth (e.g., EIF5A, HNRNPH2, LRRC47, and NVL), and migration (e.g., NOL3 and SLTM) of prostate cancer cells." (PMID 37591798, 2023).
bladder cancer (4 papers, 2021 to 2025). "More recent studies have shown that PABPN1 is linked to human cancer progression, but the role of PABPN1 in bladder cancer is unknown." (PMID 36879298, 2023). "In addition, as our previous study showed that NUDT21 inhibits bladder cancer growth and metastasis via suppressing the expression of Wnt signaling targets, we compared the genes whose APA is regulated by PABPN1 in the present study and those by NUDT21, and found few overlap target genes." (PMID 36879298, 2023).
glioblastoma (3 papers, 2022 to 2025). The most malignant astrocytic tumor (WHO grade IV). "Collectively, these findings indicated that Bcl2l2‐ Pabpn1 fusion transcript might be a novel regulator of proliferation, migration and invasion in glioblastoma." (PMID 35894779, 2022).
muscular dystrophies (3 papers, 2021 to 2022). "Extensive genetic testing has been performed in various cases, which included ALS genes (C9orf72, FUS, SOD1, TARDBP), oculopharyngeal muscular dystrophy (PABPN1), Kennedy disease (AR), panels for spinocerebellar ataxia as well as whole-exome sequencing." (PMID 33842068, 2021). "PABPN1 accumulation was reported to be useful in differentiating OPMD from other myopathies including myotonic dystrophy, inflammatory myopathies, and muscular dystrophies." (PMID 36476314, 2022).
proteinopathies (2 papers, 2022 to 2023). "There is a possibility that different cell type may have different threshold of Ala repeats for PABPN1 undergoing phase transition and thereby progressing proteinopathy." (PMID 37422193, 2023). "This study provides potential mechanisms underlying phase transition of PABPN1, sequestration of cellular essential factors, and deleterious alteration of pre-mRNA 3′-UTR processing, which may be beneficial to understanding of the cytotoxicity and proteinopathy of PABPN1." (PMID 37422193, 2023). "In addition, aggregates might also be protective by titrating misfolded PABPN1 and/or toxic oligomers, as it has been shown for other proteinopathies." (PMID 35025870, 2022).
Arrhythmia (1 paper, 2021). Any cardiac rhythm other than the normal sinus rhythm. "Whether downregulation of PABPN1 observed in dilated cardiomyopathy and OPMD results in dysregulation of Kv11.1 isoform expression and leads to the development of arrhythmias requires future investigation." (PMID 33467093, 2021).
Atrophy (1 paper, 2020). Any weakening or degeneration, especially through lack of use. "Reduced levels of the polyadenylation binding protein nucleus 1 (PABPN1), a multifactorial regulator of mRNA processing, cause muscle atrophy." (PMID 33077830, 2020).
colon cancer (1 paper, 2020). "NUDT21, CPSF3, CSTF2, and MTPAP were overexpressed while PCF11 and PABPN1 were suppressed in colon cancer tissues." (PMID 32153636, 2020).
COVID-19 (1 paper, 2024). A disease caused by infection with severe acute respiratory syndrome coronavirus 2. "Studies have also shown that compared with controls, the lung tissue of patients who died of COVID-19 had upregulated expression of proteins such as NPC1/2, CEACAM1, CTSL, EIF4E, and PABPN1, which involve virus-binding receptors, proteases, host mRNA degradation, and translation cessation." (PMID 38752128, 2024).
dyskeratosis congenita (1 paper, 2017). Dyskeratosis congenita (DC) is a rare ectodermal dysplasia that often presents with the classic triad of nail dysplasia, skin pigmentary changes, and oral leukoplakia associated with a high risk of bone marrow failure (BMF) and cancer. "Degradation of hTR is stimulated by the 3′ polyadenylation activity of the human TRAMP complex and antagonized by the poly(A)-binding protein PABPN1 and the deadenylase PARN, which is mutated in some cases of the premature aging disease dyskeratosis congenita (DKC)." (PMID 28202538, 2017).
glioma (1 paper, 2022). A benign or malignant brain and spinal cord tumor that arises from glial cells (astrocytes, oligodendrocytes, ependymal cells). "We performed paired‐end RNA‐seq of rat C6 glioma cells and normal cells and discovered a read‐through fusion transcript Bcl2l2‐Pabpn1 in which exon 3 of Bcl‐2‐like protein 2 (Bcl2l2) fused to exon 2 of Polyadenylate‐binding protein 1 (Pabpn1)." (PMID 35894779, 2022).
hypothyroidism (1 paper, 2023). Abnormally low levels of thyroid hormone. "We describe the first reported case of OPMD with detected PABPN1 gene expansion in the Philippines simulating hypothyroidism symptoms, suggesting possible points for misidentification and underdiagnosis of OPMD in developing countries." (PMID 37519616, 2023).
Infertility (1 paper, 2022). "The condensation and compartmentalization of PABPN1 is one of the mechanisms that lead to infertility of Pabpn1-knockout mice." (PMID 36306357, 2022).
Multiple Myeloma (1 paper, 2025). "In the Kaplan-Meier plotter database, increased PABPN1 expression was linked to poorer RFS in Multiple Myeloma (n = 538, HR = 1.70, P = 0.012), STAD (n = 215, HR = 2.42, P = 0.043) and TGCT (n = 105, HR = 2.72, P = 0.0096)." (PMID 40607380, 2025).
muscle degeneration (1 paper, 2013). "OPMD patient muscle degeneration initiates after midlife, while at an earlier age carriers of alanine expansion mutant PABPN1 (expPABPN1) are clinically pre-symptomatic." (PMID 23815790, 2013).
muscular atrophy (1 paper, 2025). The loss of muscle tissue due to inactivity or disease. "Mutations in the PABPN1 gene can lead to OPMD, a specific form of muscular atrophy." (PMID 40282297, 2025).
myotonic dystrophy type 2 (1 paper, 2025). Myotonic dystrophy type 2 (MD2), also known as proximal myotonic myopathy, is a very rare genetic multi-system disorder of late childhood or adult-onset characterized by mild myotonia, muscle weakness, and rarely cardiac conduction disorders. "Similarly, as discussed, testing for OPMD (PABPN1, R75) and myotonic dystrophy type 2 (CNBP (ZNF9), R410) are only available through PCR-based tests and need to be requested additionally to the panels of interest." (PMID 39349043, 2025).
ovarian carcinoma (1 paper, 2024). A malignant neoplasm originating from the surface ovarian epithelium. "The qPCR results showed that except for PABPN1, all other genes were significantly different from the control group, suggesting that the expression of differentially expressed genes may play a functional role in ovarian cancer." (PMID 38890751, 2024).
urogenital cancers (1 paper, 2025). "Subsequent exploration focused on the association between PABPN1 expression and immune cell infiltration in six urogenital cancers, revealing PABPN1’s presence across diverse clinical characteristics." (PMID 40607380, 2025). "The findings indicated that PABPN1 expression was associated with the infiltration levels of immune cell types in specific urogenital cancers." (PMID 40607380, 2025). "Additionally, the association between PABPN1 and marker genes of tumor-infiltrated immune cells in urogenital cancers was confirmed." (PMID 40607380, 2025). "Subsequently, the UALCAN database was employed to investigate PABPN1 expression in urogenital cancers with different clinical characteristics." (PMID 40607380, 2025). "Further analysis focused on the connection between PABPN1 expression and immune cell infiltration in six urogenital cancers." (PMID 40607380, 2025). "Differential expression of PABPN1 in urogenital cancers with distinct clinical characteristics was assessed using the UALCAN database." (PMID 40607380, 2025). "In summary, these results strongly supported the notion that PABPN1 expression influenced immune cell infiltration in urogenital cancers." (PMID 40607380, 2025). "The cBioPortal website was utilized to analyze genomic alterations of PABPN1 in urogenital cancers." (PMID 40607380, 2025). "Additionally, significant correlations existed between PABPN1 expression and tumor immune-infiltrated cells (TILs) in many human cancers, with marker genes of TILs showing significant relationships with PABPN1 expression, particularly in urogenital cancers." (PMID 40607380, 2025).
viral infection (1 paper, 2017). "Thus, to gain some mechanistic insight into how viral infection causes APA, we firstly knocked down four key 3′ processing factors (PABPN1, CPSF30, CFIm25 and CFIm68) to test whether viral proliferation was affected." (PMID 28233779, 2017).
cancer (20 papers, 2019 to 2025). A tumor composed of atypical neoplastic, often pleomorphic cells that invade other tissues. "We explored the potential associations between PABPN1 expression and immune subtypes, molecular subtypes in different cancer types, promising immune biomarkers, and tumor-infiltrating cells (TILs) in the tumor microenvironment (TME)." (PMID 40607380, 2025). "The preceding findings highlighted a substantial association between PABPN1 and cancer prognosis and immunity." (PMID 40607380, 2025). "Although APA site utilization is regulated by multiple nuclear RNA-binding proteins, reduced PABPN1 levels have been implicated in APA site utilization in different cancers." (PMID 38213032, 2024). "After establishing differential PABPN1 expression in distinct immune subtypes, the exploration of potential correlations with immune cell infiltration revealed significant associations in 42 cancer types." (PMID 40607380, 2025). "This study aimed to comprehensively investigate the involvement of PABPN1 in both prognosis and immunology in human cancers." (PMID 40607380, 2025). "The BioGPS database analysis was conducted to examine the expression of PABPN1 across various cancer cell lines and normal tissues." (PMID 40607380, 2025). "Based on these results, it can be concluded that PABPN1 expression varied across immune subtypes and molecular subtypes in several human cancer types." (PMID 40607380, 2025). "The prognostic significance of PABPN1 expression in human cancers was assessed through several databases." (PMID 40607380, 2025). "This emphasized the significance of PABPN1 in shaping the immune microenvironment and hinted at its potential involvement in modulating immune responses within the context of cancer in both LIHC and TGCT." (PMID 40607380, 2025). "In cervical cancer, the overexpression of PABPN1 reversed the inhibited cancer development and radio-resistance induced by the miR-1323 inhibitor." (PMID 40607380, 2025). "Further study was required to elucidate the exact pathway of PABPN1’s participation in immune regulation and its specific influence on cancer prognosis." (PMID 40607380, 2025). "The intricate relationship between PABPN1 expression and immune checkpoint genes in many cancer types warranted further investigation." (PMID 40607380, 2025). "The findings revealed a consistently high expression level of PABPN1 in almost all cancer cell lines." (PMID 40607380, 2025). "In LIHC (n = 363), BLCA (n = 405), and TGCT (n = 132), we aimed to elucidate the potential immune functions of PABPN1 across different cancer types." (PMID 40607380, 2025). "Collectively, the results substantiated our assumption that PABPN1 was a potential pan-cancer biomarker." (PMID 40607380, 2025). "In the initial phase of our investigation, we employed the TIMER, GEPIA, and BioGPS databases to assess the expression levels of PABPN1 in both cancer and normal tissues." (PMID 40607380, 2025). "PABPN1 was expected to be an important role element in cancer research, serving as a potential prognostic and immunological pan-cancer biomarker." (PMID 40607380, 2025). "The TISIDB website was utilized to investigate the impact of PABPN1 expression on immune and molecular subtypes across human cancers." (PMID 40607380, 2025). "Investigating abnormal PABPN1 methylation in the context of pan-cancer research holds significant promise as a novel direction for future research endeavors." (PMID 40607380, 2025). "This study aimed to investigate the role of poly(A) binding protein nuclear 1 (PABPN1) as a potential pan-cancer biomarker for prognosis and immunotherapy." (PMID 40607380, 2025). "Correlations between PABPN1 expression and immune checkpoints (ICP), tumor mutational burden (TMB), microsatellite instability (MSI), and neoantigens in human cancers were examined using the SangerBox database." (PMID 40607380, 2025). "PABPN1’s correlation with immune cell infiltration in the TME across different human cancers was investigated." (PMID 40607380, 2025).